IGHV3-66 (immunoglobulin heavy variable 3-66)
Description:
V region of the variable domain of immunoglobulin heavy chains that participates in the antigen recognition. Immunoglobulins, also known as antibodies, are membrane-bound or secreted glycoproteins produced by B lymphocytes. In the recognition phase of humoral immunity, the membrane-bound immunoglobulins serve as receptors which, upon binding of a specific antigen, trigger the clonal expansion and differentiation of B lymphocytes into immunoglobulins-secreting plasma cells. Secreted immunoglobulins mediate the effector phase of humoral immunity, which results in the elimination of bound antigens. The antigen binding site is formed by the variable domain of one heavy chain, together with that of its associated light chain. Thus, each immunoglobulin has two antigen binding sites with remarkable affinity for a particular antigen. The variable domains are assembled by a process called V-(D)-J rearrangement and can then be subjected to somatic hypermutations which, after exposure to antigen and selection, allow affinity maturation for a particular antigen.
Synonyms: IGHV366; VH
Gene: Immunoglobulin variable (V) gene on chromosome 14 (106,675,017 to 106,675,544, reverse strand). Ensembl gene ENSG00000211972.
Subcellular location: Secreted; Cell membrane
Gene Ontology:
Molecular function: antigen binding
Biological process: immunoglobulin mediated immune response
Cellular component: extracellular region; plasma membrane
Homologues: Paralogues in human: IGHV3-53 (97% identical), IGHV3-23 (92% identical), IGHV3-74 (89% identical), IGHV3-64 (88% identical), IGHV3-11 (86% identical), IGHV3-38 (86% identical), IGHV3-48 (86% identical), IGHV3-21 (85% identical), IGHV3-33 (85% identical), IGHV3-43 (85% identical), IGHV3-64D (85% identical), IGHV3-7 (85% identical), and 65 more.